PTGR1 (prostaglandin reductase 1)
Diseases named in the same sentence as PTGR1 in open-access papers:
PTGR1 is named in the same sentence as 37 diseases in open-access papers, as found by Europe PMC text mining. Sharing a sentence is not in itself a finding about the gene and the disease. The quoted sentences say what the papers report.
lung carcinoma (7 papers, 2017 to 2025). "PTGR1 is overexpressed in several cancer cell lines, including hepatocellular carcinoma, lung cancer, prostate cancer and bladder cancer, suggesting an oncogenic function." (PMID 40953057, 2025). "The fundamental function of PTGR1 in lung cancer progression is unclear but MITF-mediated inflammation involved in regulating PTGR1 has been proposed." (PMID 33293474, 2020). "PTGR1 is known as leukotriene B4 12-hydroxydehydrogenase (LTB4DH), which is capable of inhibiting lung cancer growth in nude mice and inactivating prostaglandins and the leukocyte chemoattractant leukotriene B4 (LTB4)." (PMID 33293474, 2020). "This extract has a strong antioxidant and repairing activity in the human lung cancer cell line (A549) as shown by the increased expression of dehydrocholesterol reductase-24 (DHCR24) and prostaglandin reductase 1 (PTGR1) genes and proteins." (PMID 28117410, 2017).
hepatocellular carcinoma (6 papers, 2017 to 2025). A malignant tumor that arises from hepatocytes. "Three of the four downregulated host genes were 0.5 < fold change < 1, while the expression of prostaglandin reduce 1 (PTGR1) was downregulated in hepatocellular carcinoma, but the difference was not statistically significant." (PMID 34249673, 2021). "Interestingly, another known NRF2-regulated gene, PTGR1 (prostaglandin reductase 1), is highly expressed in NSCLC, promotes cancer cell growth through positive regulation of the cyclin-dependent protein kinase complex, and is considered to be a druggable target in lung and hepatocellular carcinoma." (PMID 29050246, 2017).
breast carcinoma (4 papers, 2023 to 2024). "In the investigation of breast cancer stem cells, PTGR1 has been recognized as a prospective prognostic indicator associated with the condition of breast CSCs and the progression of cancers." (PMID 38256104, 2024).
prostate carcinoma (4 papers, 2021 to 2025). A carcinoma that arises from epithelial cells of the prostate gland. "One possibility is that PTGR1 might produce some metabolites, which play bigger pro-tumorigenic roles than PGE2 and LTB4 in multiple types of cancer cells, including at least TNBC and prostate cancer." (PMID 34421612, 2021).
clear cell renal carcinoma (2 papers, 2023 to 2024). A malignant epithelial neoplasm of the kidney characterized by the presence of lipid-containing clear cells within a vascular network. "Considering these criteria 36 of the total number of 389 TCGA cases (~ 9%) indicated the presence of both NER deficiency and significant PTGR1 expression levels thus defining the proportion of clear cell renal carcinoma cases that may respond to irofulven therapy." (PMID 37996508, 2023). "Conversely, diminished expression of PTGR1 is correlated with unfavorable prognosis in ovarian cancer, endometrial cancer, and renal clear cell carcinoma." (PMID 38256104, 2024).
lung adenocarcinoma (2 papers, 2020 to 2021). A carcinoma that arises from the lung and is characterized by the presence of malignant glandular epithelial cells. "These correlations were then extended to TCGA analysis of 517 lung adenocarcinoma patients, out of which 35% showed elevated PTGR1, and 40% of those further displayed statistically significant co-occurrence of KEAP1 mutations." (PMID 33889302, 2021). "We showed that MITF binds to the promoter of PTGR1 and downregulates PTGR1 expression in lung adenocarcinoma." (PMID 33293474, 2020).
acute kidney injury (1 paper, 2026). Sudden and sustained deterioration of the kidney function characterized by decreased glomerular filtration rate, increased serum creatinine or oliguria. "Using butterflies as an evolutionary model, we identify PTGR1, the human PGR homolog, as a potential target of AA resistance, which is associated with human acute kidney injury." (PMID 41486087, 2026).
breast invasive carcinoma (1 paper, 2021). "We have checked the mRNA level of these genes in TCGA breast invasive carcinoma and found that FOXA1, PTGR1 and MTHFR showed an obvious negative correlation with miR‐522 level." (PMID 33369228, 2021).
colon adenocarcinoma (1 paper, 2022). "While low expression of SUCLG2 (p < 0.001), PTGR1 (p = 0.001), ELOVL6 (p = 0.013) and CPT2 (p < 0.001) were correlated with poor overall survival of colon adenocarcinoma patients." (PMID 36568396, 2022).
kidney cancer (1 paper, 2023). Primary or metastatic malignant neoplasm involving the kidney. "PTGR1, a functionally validated prerequisite of irofulven sensitivity, is expressed in several kidney cancer cell lines." (PMID 37996508, 2023).
leukemia (1 paper, 2023). A malignant (clonal) hematologic disorder, involving hematopoietic stem cells and characterized by the presence of primitive or atypical myeloid or lymphoid cells in the bone marrow and the blood. "We also determined that the average expression of PTGR1 is about two-fold lower in primary tumor samples from leukemia and lymphoma patients than those from solid tumor patients in the cancer genome atlas (TCGA) studies." (PMID 37306526, 2023).
melanoma (1 paper, 2020). A malignant, usually aggressive tumor composed of atypical, neoplastic melanocytes. "We found that ANXA1, FZD7 and PTGR1 were MITF direct targets in CL1-0 cells, but these genes were not regulated in melanoma 501MEL cells." (PMID 33293474, 2020).
squamous cell tumours (1 paper, 2024). "In contrast, PTGR1 was associated with a lower risk of ever smoking and with squamous cell tumours [OR: 0.79, 95% CI: 0.72 to 0.87; PP4: 0.99]." (PMID 38684708, 2024).
steatosis (1 paper, 2025). Increased lipid within the cytoplasm of cells. "Of 12 proteins in the SomaSignal test for steatosis, two (PTGR1 and GUSB) showed a statistically significant lower abundance for semaglutide 0.4 mg versus placebo." (PMID 40691365, 2025).
triple-negative breast carcinoma (1 paper, 2019). An invasive breast carcinoma which is negative for expression of estrogen receptor (ER), progesterone receptor (PR), and human epidermal growth factor receptor 2 (HER2). "Such combined action was efficient in triple-negative breast cancer and linked with the expression of prostaglandin reductase 1 (PTGR1)." (PMID 31934267, 2019).
tumor (16 papers, 2018 to 2025). "To assess the clinical relevance of NRF2 pathway activation in OAC primary tumours, we employed four NRF2 targets (KIAA0319, ARID3A, HSPA1B, PTGR1) from clusters 2 and 9 to calculate the risk score based on datasets from The Cancer Genome Atlas (TCGA)." (PMID 40473905, 2025). "LP-184 is specifically activated in tumor cells to an active compound by the oxidoreductase enzyme prostaglandin reductase 1 (PTGR1), that is frequently overexpressed in multiple solid tumor types." (PMID 38630886, 2024). "Downregulation of PTGR1 will likely render tumor cells resistant to irofulven, therefore the expression of this enzyme should be verified in the diagnostic setting before administration." (PMID 37996508, 2023). "The expression levels of the distinct genes of the RvD pathway ALOX15, ALOX15, FPR2, GPR18, GPR32, HPGD and PTGR1 were leveraged from 516 bulk tumor HNSC RNA-seq data, profiled by TCGA and plotted as a heatmap of individual tumor samples." (PMID 35742918, 2022). "AGTRAP1, ABCC5, SH3KBP1, and RBMX were upregulated, while PTGR1 was downregulated in tumor samples as compared to normal samples." (PMID 36338975, 2022). "As a next generation member of the class of acylfulvene prodrugs, the anti-tumor activity of LP-184 is likely to be dependent upon the oxidoreductase activity of PTGR1." (PMID 33889302, 2021). "Data from the KM-plotter and Pan-cancer database suggests that high PTGR1 expression correlates with poor prognosis in a variety of tumor types, such as triple-negative breast cancer (TNBC), lung, gastric, head and neck, pancreatic and liver cancer." (PMID 34421612, 2021). "In general, the bioactivation and anti-tumor activity of the acylfulvene class of prodrugs appears to be based on the enzymatic action of PTGR1." (PMID 33653269, 2021). "This suggests that acylfulvenes like LP-184 will be suited for patients exhibiting elevated tumor levels of PTGR1." (PMID 33653269, 2021). "Acylfulvene anti-tumor activity appears to be based on activation through reductive mechanisms that are mediated by enzymes such as Prostaglandin Reductase 1 (PTGR1)." (PMID 33889302, 2021). "Illudin derivatives may offer selective targeting due to reliance on enzyme Prostaglandin Reductase 1 (PTGR1) to the desired tumor types, which can lead to optimal results by controlling off-target toxicity in ADCs." (PMID 39186767, 2024). "Multiple studies reported the involvement of PTGR1 in tumor development." (PMID 39309426, 2024). "In Yap1KD; Gp130FF tumor organoids, we found reduced transcript levels for Igsf9 (marker for cell proliferation), Cyp2c65, (lipid and glucose metabolism), Ptgr1 and Sult1c2 (metabolite biosynthesis), and Clca1 (mucosal defence) when compared with Yap1WT; Gp130FF tumor." (PMID 37957015, 2024). "Whether and how these pathways relate to LP-184 anti-tumor cytotoxicity, or specifically relate to the PTGR1-mediated activation of LP-184, warrants further investigation." (PMID 33889302, 2021). "In addition to key mechanistic knowledge on tumor specificity related to acylfulvene activation by PTGR1 and tumor resistance determined by TC-NER pathway components, there remain additional pathways known to be associated with their activity." (PMID 33653269, 2021). "The expression levels of CD36, PTGR1, SUCLG2 and CPT2 were significantly decreased in tumor tissues." (PMID 36568396, 2022). "Third, both PTGR1 upstream substrate PGE2 and direct substrate LTB4 play important roles in cancer progression through promoting tumor growth." (PMID 34421612, 2021). "Unlike illudin S, acylfulvene tumor specificity appears to be based on a tumor-selective activation through reductive mechanisms that are mediated by enzymes such as Prostaglandin reductase 1 (PTGR1), or leukotriene B4 12-hydroxydehydrogenase." (PMID 33653269, 2021).
tumor (continued). "In ALDH+CD24-CD44+ BCSCs, we identified P4HA2, PTGR1 and RAB40B as potential prognostic markers, which were virtually related to the status of BCSCs and tumor growth in TNBC cells." (PMID 29471829, 2018). "PTGR1, C1orf115, CRYL1, ALDOB, and SULT1B1 may be tumor suppressor genes involved in GC progression." (PMID 38737262, 2024). "Indeed, this tumor expressed six of the NRF2 targets (CES1, CYP4F1, GSTM3, ARK1C1/3/4, AKR1C2, SRXN1, and PTGR1) more than 16-fold above their respective mean expressions for the entire cohort and 24 proteins more than 4-fold above their means." (PMID 37716475, 2023). "The expression of CD36, PTGR1, SUCLG2, CPT2 and ELOVL6 were downregulated in tumor tissues." (PMID 36568396, 2022).
cancer (15 papers, 2017 to 2025). A tumor composed of atypical neoplastic, often pleomorphic cells that invade other tissues. "The dysregulation of PTGR1 is associated with several cancers or diseases." (PMID 38413664, 2024). "Since PTGR1 is overexpressed in several cancer cell lines, including those from stomach, liver, lung, and prostate cancers, PTGR1 may cause cancer." (PMID 38256104, 2024). "PTGR1 is overexpressed in various cancer cell lines, promoting cancer cell proliferation and increasing resistance to cancer oxidative stress." (PMID 38413664, 2024). "We compared PTGR1 RNA expression between 180 hematologic and 856 solid cancer cell lines covered by the cancer cell line encyclopedia (CCLE)." (PMID 37306526, 2023). "We then utilized flow cytometric analysis to demonstrate that upregulated PTGR1 can effectively abrogate metformin-induced G0/G1 arrest and promote S and G2/M-phase entry in cancer cells." (PMID 37582751, 2023). "The dependence on PTGR1 provides a patient-selection strategy for irofulven and LP-184 but limits their applications in cancer cells with low PTGR1." (PMID 37306526, 2023). "PTGR1, as an inducible enzyme with enone reductase activity, demonstrated therapeutical potential for cancer treatment." (PMID 36568396, 2022). "Together, these studies suggest that PTGR1 plays a role in cancer cell proliferation and can be of interest as a potential target for cancer therapy." (PMID 34421612, 2021). "Future studies should investigate the role of PTGR1 metabolites and focus on better understanding the inhibitory mechanisms of PTGR1 in cancer progression." (PMID 34421612, 2021). "Although PTGR1 is a promising therapeutic target for cancer therapy, currently only a few PTGR1 inhibitors have been reported." (PMID 34421612, 2021). "In this review, we summarize the progress made in recent years toward the understanding of PTGR1 function and structure, highlight the roles of PTGR1 in cancer, and describe potential inhibitors of PTGR1." (PMID 34421612, 2021). "In this context it is thus considered desirable to have PTGR1-based sensitivity for enhancing cancer drug selectivity and targeting aggressive cancers." (PMID 33653269, 2021). "In recent years, a growing body of literature has emphasized that metabolic enzyme PTGR1 plays a significant role in cancer and is a novel potential therapeutical target for cancer treatment." (PMID 34421612, 2021). "Recently, multiple studies also provided further evidence to support that the expression level of PTGR1 was related with cancer prognosis." (PMID 34421612, 2021). "These modulators will serve as chemical tools to further investigate the function of PTGR1 and drug leads for future cancer treatment." (PMID 34421612, 2021). "This looks like in contrast with those studies demonstrating that knockdown of PTGR1 was able to inhibit cancer cell proliferation." (PMID 34421612, 2021). "A growing evidence suggested that PTGR1 plays a significant role in cancer and has emerged as a novel target for cancer therapeutics." (PMID 34421612, 2021). "It has also been suggested that PTGR1 may be involved in the proliferation of cancer cells and may be a potential target for treating cancer." (PMID 38737262, 2024). "Previous studies indicated that PTGR1 was present in several cancer progresses." (PMID 37910537, 2023). "Currently limited information is available regarding the role of PTGR1 in cancer progression." (PMID 34421612, 2021). "However, comparatively little is known why the correlation of PTGR1 and cancer survival exists in other cancer types and has opposing directions in different cancer types." (PMID 34421612, 2021). "Interestingly, PTGR1 has also been linked to not only HMAF and other prodrug sensitivity, but also cancer oxidative stress." (PMID 34421612, 2021). "Fourth, the correlation of PTGR1 and cancer survival remains questionable." (PMID 34421612, 2021).
cancer (continued). "PTGR1 has alkenal/one oxidoreductase activity, suggesting that it might have an antioxidant effect against cancer oxidative stress." (PMID 34421612, 2021). "Studies in a variety of cancer types have reported PTGR1 is involved in progression and malignancy." (PMID 33653269, 2021). "These methods would provide more evidence to answer whether PTGR1 is a novel biomarker for cancer prognosis." (PMID 34421612, 2021). "It suggested that PTGR1 could be a potential therapeutic target for cancer." (PMID 37910537, 2023). "However, the expression level of PTGR1 remains very low in cancer cells of hematologic lineages." (PMID 37306526, 2023). "Therefore, PTGR1 is a novel potential therapeutical target for cancer treatment." (PMID 34421612, 2021). "In addition, PTGR1 inhibitor might sensitize cancer cells to ROS-induced cell death, which could be used to develop novel combination cancer treatment." (PMID 34421612, 2021). "Although its function in GC has not been studied, research has shown that PTGR1 is involved in the progression of many cancers." (PMID 38737262, 2024). "It is not completely clear how PTGR1 affects cell proliferation, but it appears to affect cancer cell proliferation in various cancers." (PMID 36509429, 2023). "Toxicity of acylfulvenes requires intracellular reduction that is believed to be mainly mediated by PTGR1, which is highly expressed in a variety of cancer models and patient samples, and appears as a part of various prognostic or predictive models in cancer that are not necessarily drug-specific." (PMID 33653269, 2021). "We tested whether predictions would perform similarly in non-NCI-60 cancer cell lines, so we selected 37 solid-tumor lines from the Cancer Cell Line Encyclopedia (CCLE) that covered those having either the low- or high-end of PTGR1 expression in microarray data." (PMID 33653269, 2021).
infection (3 papers, 2011 to 2022). The state of being infected such as from the introduction of a foreign agent such as serum, vaccine, antigenic substance or organism. "These include perilipin 2 (PLIN2), which was increased subsequent to primary infection by E. acervulina and E. maxima, as well as prostaglandin reductase 1 (PTGR1), CD36, and carnitine O-octanoyltransferase (CROT), which were decreased following E. acervulina primary infection." (PMID 22140460, 2011).
adenocarcinoma (1 paper, 2021). A common cancer characterized by the presence of malignant glandular cells. "In an analysis of 533 NSCLC adenocarcinoma patient records from the TCGA portal, PTGR1 was found to be highly expressed in KEAP1 mutated samples." (PMID 33889302, 2021). "Similarly, in a complementary analysis exploring clinical data from TCGA, we determined that greater than 35% of a total of 517 NSCLC adenocarcinoma patients expressed elevated PTGR1 transcript levels." (PMID 33889302, 2021).
hematologic cancer (1 paper, 2023). "Insufficient PTGR1 indicated the limited application of existing acylfulvenes for hematologic cancers." (PMID 37306526, 2023). "We observed significantly lower expression of PTGR1 in hematologic cancer cell lines with a mean normalized microarray intensity of 4.2 compared to a mean value of 8.7 in solid cancer cell lines." (PMID 37306526, 2023). "It was hypothesized that LP-284 could be applied to hematologic cancer cells with limited PTGR1 expression which has posed a barrier for irofulven and LP-184." (PMID 37306526, 2023).
prostate (1 paper, 2022). "Similarly to SMARCD1, we found that numerous downstream targets of SMARCD2 (e.g., PTGR1, TRMP8, PGC) and SMARCD3 (e.g., EGF, PIK3AP1, HSD3B1) were AR-driven genes that are involved in prostate tumorigenesis, progression and metastasis." (PMID 36611918, 2022).
PTGR1 also shares sentences with these, for which no sentence is quoted: bladder cancer (2 papers); liver cancer (2); myocardial infarction (2); ovarian carcinoma (2); endometrial cancer (1); gastric cancer (1); glioma (1); head and neck squamous cell carcinoma (1); lymphoma (1); pancreatic cancer (1); periodontitis (1); renal cell carcinoma (1); Ta (1); tuberculosis (1); urothelial cell carcinoma (1); uterine corpus endometrial carcinoma (1).